GSK3B (glycogen synthase kinase 3 beta)
Diseases named in the same sentence as GSK3B in open-access papers (continued):
Sharing a sentence is not in itself a finding about the gene and the disease.
tumor (continued). "The potentiation of YY1 and GSK3β by O-GlcNAcylation will drive changes in metabolism in tumours and tumour microenvironment cells in association with their regulation of the melatonergic pathway." (PMID 33375613, 2020). "Tumor-associated GSK-3β is correlated with reduced expression of retinoic acid receptor-β (RARβ), which is caused by GSK-3β-mediated phosphorylation and heterodimerization abrogation of retinoid X receptor (RXRα) with RARα on RARβ promoter." (PMID 31938062, 2020). "Overall, our results revealed that MACROD2 is frequently affected by SVs in HCC, and its deficiency promotes tumor growth and metastasis by activating GSK-3β/β-catenin signaling." (PMID 32257385, 2020). "Here we describe the pathological roles of deregulated GSK3β within the major hallmark properties of cancer, including tumor cell survival and proliferation, invasion, resistance to therapy and the tumor “stemness” phenotype." (PMID 32503133, 2020). "Building upon this background knowledge, in the present study we investigated the putative pathological roles for GSK3β in ESCC and explored the effects of GSK3β inhibition against this tumor type and the underlying biological mechanisms." (PMID 32678196, 2020). "Pharmacological activation of this receptor in CRC by activation of AKT/PKB signaling and subsequent inhibition of GSK3β has been associated with tumor progression and an increase in tumor cell proliferation." (PMID 32488850, 2020). "We also documented how tumor types that acquire pro-invasive capacity as they evade therapeutic insults are also susceptible to experimental therapy that targets GSK3β." (PMID 32503133, 2020). "Dysfunction of GSK-3β is an active element in cell proliferation that is associated with cancer, and it is overexpressed in certain tumor types, including colon cancer, liver cancer, ovarian cancer, and pancreatic cancer." (PMID 32973135, 2020). "Taken together, the present study reinforces the notion that GSK3β is a potential therapeutic target in ESCC, thereby including this as another tumor type susceptible to GSK3β-targeted therapy." (PMID 32678196, 2020). "Considering the risk of tumor recurrence due to suppression GSK-3β, we assessed the relationship between MSC transplantation and recurrence of HCC." (PMID 31024348, 2019). "Western blot analysis on the xenograft tumor tissues further confirmed that the reduced tumorigenicity was associated with the inactivation of GSK3β/mTORC1 signaling and its downstream molecules, and the cellular proliferation marker PCNA." (PMID 30523261, 2018). "GSK3β is also considered an important transcription factor involved in the Wnt signal pathway, which is associated with tumor growth and metastasis." (PMID 30166525, 2018). "GSK3β is also considered an important transcription factor involved in the Wnt signal pathway, which is associated with tumor growth and tumorigenicity." (PMID 30166525, 2018). "DISC1 expression was negatively associated with phosphorylated (p-) GSK3β, but positively correlated with a more invasive tumor phenotype and predicted poor NSCLC patient prognosis." (PMID 29029423, 2017). "It was previously reported that PI3K/AKT/GSK3β pathway regulates β-Catenin activity and that down-regulation of β-catenin expression is associated with more aggressive tumor phenotypes." (PMID 28978070, 2017). "AKT activation was linked to mTORC1 and GSK-3β/β-catenin signaling, which are primarily associated with tumor cell growth and metastasis, respectively." (PMID 28184024, 2017). "GSK3β is a multifunctional kinase and member of Wnt/β-catenin pathway, which is implicated in normal tissue development and tumor initiation as well as SC fate control." (PMID 28831205, 2017). "Knockdown of GPR48/LGR4 in tumor cells was significantly associated with reduced phosphorylation of Ser9 of GSK3β and ERK1/2, resulting in downregulation of β-catenin signaling." (PMID 29383135, 2017).
tumor (continued). "Tumor #1 and Tumor #2, the two different sections that belong to the same patient, showed mutations in GSK3β (at a variant allele frequency of approximately 50%)." (PMID 27057633, 2016). "We also demonstrated that DDA1-mediated tumor progression is associated with the activation of the NFκB/COP9 signalosome 2(CSN2)/glycogen synthase kinase3β (GSK3β) pathway." (PMID 26942699, 2016). "Daily intraperitoneal injection of Z86 at 5 mg/kg resulted in >70% reduction in the tumor weight of HCT116 cell origin that was associated with decreased GSK3β (Ser9) phosphorylation and increased β-catenin phosphorylation." (PMID 27551464, 2015). "The effects of GSK3β inhibition on tumor invasion, susceptibility to gemcitabine, MMP-2 expression and FAK phosphorylation were observed in tumor xenografts." (PMID 23408967, 2013). "As such, loss of PTEN function and /or increased AKT activity in tumor cells results in strong suppression in GSK3β activity." (PMID 23388100, 2013). "In a previous study, we demonstrated that GSK3β inactivation is associated with tumour stage of NPC through regulation of PMS2." (PMID 23874688, 2013). "GSK3β is a proline-directed serine-threonine kinase, involved in many cellular processes, such as metabolism, neuronal development, and body pattern formation, and GSK3β signaling has also been implicated in mental illness and tumor formation." (PMID 23626687, 2013). "In this respect, evidence shows that both chemical inhibitors-caused GSK3β inactivation and small interference RNA-mediated gene silencing are responsible for tumor inhibition." (PMID 24312384, 2013). "Activated Akt causes tumor cell survival and inhibits of apoptosis by phosphorylating numerous downstream targets including mTOR and GSK3β." (PMID 22899960, 2012). "Nuclear GSK3β was inversely associated with tumor stage [p = 0.02; OR = 0.3; (95% CI = 0.142-0.838)] and histological grading [p = 0.05; OR = 0.417 (95% C.I = 0.172-1.01)] in IDCs." (PMID 19751508, 2009). "Our study also demonstrated significant correlation between GSK3β nuclear localization and tumor grade (p = 0.02), suggesting its association with tumor progression." (PMID 19751508, 2009). "GSK-3β overexpression was associated with poor prognosis and was found to influence tumor stemness, immune modulation, and key signaling pathways that drive tumor progression and therapeutic resistance." (PMID 41321870, 2025). "Further analysis revealed that GSK-3β was linked to tumor stemness- and immune-related pathways." (PMID 41321870, 2025). "9-ING-41, a novel ATP-competitive small-molecule inhibitor that targets glycogen synthase kinase-3β (GSK-3β), has emerged as a promising therapeutic agent because of its ability to disrupt oncogenic signaling pathways associated with tumor progression and treatment resistance." (PMID 41220107, 2025). "For example, increased levels of miRNA-26a have been observed in human CCA tissues compared with non-tumor biliary cells, which has been associated with the fact that this miRNA leads to a reduction in GSK-3β activity and thus the activation of the Wnt/β-catenin signaling pathway." (PMID 37190050, 2023). "GSK3β may also play a positive role in cancer cell proliferation, because a reduced expression of GSK3β was negatively associated with tumor cell survival and proliferation." (PMID 37373005, 2023). "Interestingly, treatment with GSK3β inhibitor CHIR can rescue the lipid accumulation defect or reverse cell growth/tumor inhibition caused by the expression of FBXW7β." (PMID 37202390, 2023). "In T cells targeting tumor, overactivity of Gsk3β has been linked to poor tumor control." (PMID 35573704, 2022). "In tumour cells, however, the Wnt/β‐catenin signal transduction pathway is activated, and the destruction complex is also destroyed, resulting in loss of the GSK‐3β‐dependent phosphorylation of β‐catenin." (PMID 34687144, 2021).
tumor (continued). "However, in HCCs, SIRT3 acts as a tumor suppressor, as it mitigates ROS-induced hepatocellular injury and interacts with glycogen synthase kinase 3 beta (GSK-3β) to induce Bax translocation to the mitochondria, causing apoptosis." (PMID 33920670, 2021). "GSK3-β was shown to promote the degradation of several proteins involved in proliferation, such as β-catenin, c-Myc, or Cyclin D and is therefore associated with anti-tumour suppression activity." (PMID 31362447, 2019). "We assessed whether the reduction of viability by combination therapy with kenpaullone and TMZ was associated with induction of apoptosis since inhibition of GSK3β is related to apoptosis in tumor cells via several signaling pathways." (PMID 31296906, 2019). "Several studies suggested a possible role of GSK-3β as a tumor suppressor gene in HCC10–12, and consequently loss of GSK-3β expression and/or inhibition of its activity may contribute to HCC development." (PMID 29445085, 2018). "Furthermore, in our small clinical cohort, increased levels of GSK-3β were associated with poorly differentiated tumours as well as recurrence and those that had died of the disease." (PMID 28930226, 2017). "In this study, we utilize small molecule inhibitors of GSK3β or phospho-incompetent mutations that individually target the known sites of phosphorylation to determine how inhibiting these events on PAX3-FOXO1 affects ARMS tumor phenotypes." (PMID 25821947, 2015). "A role for aberrant GSK3β in these tumor types is supported by the observation that pharmacological inhibition of its activity reduces the survival and proliferation of cancer cells and predisposes them to apoptosis in vitro and in tumor xenografts." (PMID 23408967, 2013). "A pathologic role for GSK3β is supported by observations that inhibition of its activity reduced the survival and proliferation of different cancer cell types, predisposing them to apoptosis both in vitro and in tumor xenografts." (PMID 24212624, 2011). "We also observed an inverse association of nuclear GSK3β with tumor grade (p = 0.02), suggesting that the initial tumor development probably requires a rapid and effective repression of GSK3β and stabilization of Slug, thereby inhibiting the expression of E-cadherin." (PMID 19751508, 2009). "However, GSK-3β’s role in cancer development is still debated, since GSK-3β may act as tumor suppressor or tumor promoter and, depending on the cancer type, the cancer development could be linked to GSK-3β’s overexpression or to its downregulation." (PMID 37108703, 2023). "Therefore, some mutations might impact the activity of GSK-3β as either a tumor suppressor or a tumor promoter, depending on the downstream targets and tumor types." (PMID 35681507, 2022). "Interestingly, tumor-associated GSK-3β was inversely correlated with RARβ expression." (PMID 31938062, 2020). "One study demonstrated that interleukin-1β, secreted by tumor-associated macrophages (TAMs), might increase the availability of β-catenin via the phosphorylation of GSK3β in colon cancer cells, thereby disrupting the function of the β-catenin destruction complex." (PMID 31616443, 2019). "SCs drive epithelial–mesenchymal transition (EMT) and enhance metastatic potential in lung cancer through pathways involving CXCL‐5/CXCR‐2/PI3K/AKT and GSK‐3β/Snail–Twist, demonstrating distinct tumor‐promoting behavior." (PMID 41583906, 2026). "Mechanistically, PCDH10 enhanced GSK-3β phosphorylation at Try216, inhibited aberrant β-catenin activation and upregulated the expression of the tumor-suppressive nuclear envelope protein LMNA expression through direct binding." (PMID 41608634, 2026). "The PI3K/AKT/GSK3β signaling pathway is a frequently dysregulated signaling cascade in various human tumor types." (PMID 41141389, 2026).
tumor (continued). "A tumor GSK-3β score ≥ 6 independently predicted nodal metastasis after adjusting for standard clinicopathological variables (adjusted odds ratio = 8.8, 95% confidence interval: 1.9-39.6; p = 0.005), with an area under the curve (AUC) of 0.84." (PMID 41558538, 2026). "This involves its interaction with GABA‐B receptors, where studies have demonstrated that GABA activation of these receptors in tumor cells inhibits GSK‐3β activity, thereby enhancing β‐catenin signaling." (PMID 41583906, 2026). "Investigations concerning HCC have revealed elevated expression levels of GSK-3β in tumor tissues, with higher levels correlating with poor patient prognosis." (PMID 40656954, 2025). "At the same time, consistent results were observed in the GSK3B-IN groups in that GSK3B downregulation mediated macrophage M1 polarization (CD86 marker) in tumor cells." (PMID 40548257, 2025). "AKT can reduce the activity of GSK3β by phosphorylating the Ser9 site of GSK3β, thereby promoting glucose uptake and utilisation in tumour cells and increasing the energy supply of tumour cells." (PMID 39778006, 2025). "Further, the current study exhibited that free DOX or DOX-CT-MNPs significantly upregulate the expression of PTEN and GSK3β tumor suppressor genes which further led to a decline in MAKP1 that promotes cell growth and proliferation blockage." (PMID 41039030, 2025). "The in vivo studies with Gsk3β KD cells in the mouse prostate resulted in tumor growth retardation compared to scramble cells." (PMID 39821099, 2025). "In cervical cancer, exosome-derived miR-1323 from cancer-associated fibroblasts downregulates PABPN1, which then recruits IGF2BP1 to stabilize GSK-3β mRNA, activating Wnt/β-catenin signaling and promoting tumor progression and radio resistance." (PMID 41516083, 2025). "Proteins were extracted from tumor nodules and followed by Western blots, showing upregulation of p-β-catenin and GSK-3β and downregulation of CELSR2 and β-catenin in the siRNA MNPs group compared to the control group." (PMID 41184253, 2025). "TAM-derived LGMN increases macrophage infiltration and tumor progression through the GSK3β/STAT3 axis." (PMID 40131864, 2025). "A growing body of evidence reports that in cancer models, certain GSK3β inhibitors can improve tumor sensitivity to chemotherapeutic agents." (PMID 40943055, 2025). "The expression levels of p-GSK-3β and p-p70S6K in tumor tissues with overexpression of catalase or GPX were greatly decreased." (PMID 39660100, 2025). "GSK3β is an important kinase whose dysregulation promotes tumor resistance, evasion of cell death, and proliferation and invasion of cancer cells." (PMID 40573233, 2025). "Inhibition of GSK3B sensitized tumor response to Olaparib with a significant decrease in tumor volume and weight compared with tumors treated with Olaparib alone in both BRCA1-proficient as well as BRCA1-deficient 4T1 tumors." (PMID 41243969, 2025). "In vivo studies further demonstrated that GSK3β inhibition decreased metastasis in a mouse xenograft model and suppressed tumor growth." (PMID 40072085, 2025). "As the first substrate of AKT, GSK3β is involved in tumor formation and progression and acts as a tumor suppressor because its activation accelerates the degradation of oncogenes such as cyclin D1 and c-Myc." (PMID 40814339, 2025). "This dual effect on stemness and therapeutic resistance highlights GSK-3β as a promising target for novel combination therapies aimed at eradicating resistant tumor subpopulations in TNBC." (PMID 41321870, 2025).
tumor (continued). "Salvigenin impedes aerobic glycolysis and enhances sensitivity to 5-fluorouracil(5-FU) in HCC cells by inhibiting the PI3K/AKT/GSK-3β pathway, restraining tumor growth in nude mice and promoting apoptosis." (PMID 40606973, 2025). "Western blot analysis showed that RARS1 knockdown reduced PI3K and phosphorylat-AKT(p-AKT) levels, while increasing GSK3β expression, suggesting that RARS1 modulates the PI3K/p-AKT/GSK3β signaling pathway in tumor proliferation and migration." (PMID 41451236, 2025). "IHC analyses of tumor tissues from HCC patients suggested that the levels of p-GSK3β and β-catenin were positively correlated with NUAK1 expression." (PMID 39901136, 2025). "GSK-3β is considered a potential tumor suppressor because it phosphorylates and targets pro-oncogenic molecules, including c-Jun, c-Myc, cyclin D1 and β-catenin, for ubiquitin-dependent proteasomal degradation." (PMID 41220107, 2025). "The PI3K/AKT/GSK3β signaling pathway is pivotal in regulating various aspects of tumor biology, including cell growth, metabolism, and migration." (PMID 41451236, 2025). "Although GSK3β is abundantly expressed in a range of human cancers, its specific function as a tumor promoter or suppressor is still under debate." (PMID 41153674, 2025). "GSK-3β knockdown in NSCLC cell lines reportedly causes apoptosis, limits cell motility, arrests tumor cells in the G0/G1 phase, and suppresses cell proliferation." (PMID 41217667, 2025). "As a key enzyme in inflammation and immune response, the downregulation of COX2 offers additional insight into the role of GSK-3β in shaping the tumor microenvironment." (PMID 41321870, 2025). "One of its downstream targets, glycogen synthase kinase 3 beta (GSK3β), is inactivated by phosphorylation at Ser9, which contributes to tumor progression." (PMID 40649280, 2025). "GSK-3β has been shown to function as a tumor suppressor protein that controls cell fate determination and stem cell maintenance by inhibiting the Wnt, Hedgehog, and Notch pathways." (PMID 40157890, 2025). "GSK3β has long been recognized as a tumor suppressor, as it suppresses WNT/β-catenin signaling and EMT51,52." (PMID 39762409, 2025). "The low expression of GSK3β was shown to be unfavorable in our cohort, which would suggest it has a tumor suppressor role in TNBC." (PMID 41465855, 2025). "We then investigated its association with tumor stemness–related and immune-related genes and performed gene set enrichment analysis (GSEA) to identify key pathways regulated by GSK-3β." (PMID 41321870, 2025). "AKT/GSK-3β activation promotes tumor growth, metastasis, and EMT formation (the expression of EMT markers such as Vimentin, and Snail)." (PMID 40265472, 2025). "IHC analyses of tumor tissues from 20 HCC patients suggested that the levels of p-GSK3β were positively correlated with NUAK1 expression." (PMID 39901136, 2025). "Canonical Wnt signaling plays a key role in tumor cell proliferation which correlates with the accumulation of β-catenin resulting inactivation of the network of targets such as GSK3β, Axin, CK1." (PMID 40193825, 2025). "GSK-3β activity also plays a role in the negative regulation of MMPs, which are critical for the degradation of extracellular matrix and thus key in tumor invasion and metastasis." (PMID 39948552, 2025). "In CD8+ T cells, inhibition of GSK3β enhances cytotoxicity, but total GSK3 deficiency promotes T cell exhaustion and accelerates tumor growth, underscoring the functional divergence between single and double deletion." (PMID 41300341, 2025). "In OC, hypoxia has been demonstrated to stimulate the production of miR‐9‐5p, accelerating migration, invasion, and tumor proliferation through the PI3K/AKT/mTOR/GSK3β, thereby recognizing miR‐9 as a prospective oncogenic driver and therapeutic target." (PMID 40740483, 2025). "By regulating tumor stemness, immune modulation, and critical signaling pathways, GSK-3β contributes to tumor progression and therapeutic resistance." (PMID 41321870, 2025).